CRP (C-reactive protein)
Diseases named in the same sentence as CRP in open-access papers (continued):
Sharing a sentence is not in itself a finding about the gene and the disease.
endometriosis (continued). "Semi‐quantitative detection of C‐reactive protein (CRP), cancer biomarkers carcinoembryonic antigen (CEA) and cancer antigen 125 (CA‐125), and endometriosis biomarker CA‐125 is demonstrated." (PMID 40411388, 2025). "DII scores were assessed for the role of food on inflammatory biomarkers, such as IL-6, C-reactive protein, and TNF-a, all of which increased in endometriosis." (PMID 39683382, 2024). "Retrospective data analysis of CRP, WBC and body temperature courses following colorectal surgery for DE at a tertiary referral center for endometriosis." (PMID 34338850, 2022). "In an endometriosis rat model, the angiotensin II receptor blocker losartan reduced TGF-β, and the surface area of endometriosis lesions was decreased as were the plasma levels of the angiogenic factors and inflammatory markers VEGF, TNF-α, PTX-3, and CRP." (PMID 35628346, 2022). "CRP and white blood cell count (WBC) levels were also significantly increased in patients with major surgical complications after bowel resection for endometriosis." (PMID 34338850, 2022). "The levels of inflammatory factors (like CRP, IL-6, IL-8, and TNF-a) in the peripheral blood and peritoneal fluid of patients with endometriosis are increased." (PMID 35800055, 2022). "Many studies on the role of other biomarkers in endometriosis (e.g., TNF-α, IL-6, VEGF, and CRP) have been conducted recently." (PMID 25006484, 2014). "The CRP frequency in the groups of women with and without endometriosis was two persons (5.4%) and one person (2.7%) respectively." (PMID 38343663, 2024). "Nevertheless, our 1-sample mendelian randomization did not observe any effect of CRP PRS on endometriosis." (PMID 36652249, 2023). "In a recent prospective study, the serum levels of CRP were compared between an endometriosis group and a control group, but no statically significant difference was observed between the two groups." (PMID 37623476, 2023). "Previous studies have shown that consumption of legumes reduces inflammatory markers such as CRP, TNF-α, IL-6, and other adhesion molecules, as well as the levels of adiponectin that may provide a mechanistic role of legumes in endometriosis." (PMID 36138433, 2022). "When compared to controls, CRP plasma levels were comparable (p = 0.12) or not-significantly elevated (p = 0.06) in women with endometriosis using either the classical CRP assay or the hsCRP assay, respectively." (PMID 21827658, 2011). "Due to comparable plasma CRP and hsCRP levels between women with stage I-II endometriosis and controls, the ROC curve analysis was not useful and it was not possible to develop the optimal cut-off point for the diagnosis of stage I-II endometriosis." (PMID 21827658, 2011). "CRP levels were measured by hsCRP and classical CRP assays in plasma of 204 women with endometriosis and 91 women without endometriosis." (PMID 21827658, 2011). "A previous study on 23 patients who underwent extensive surgery, either hysterectomy and/or resection of deep infiltrating endometriosis leaving large areas of peritoneal defects, reported no local infections and a low frequency of transitory high CRP levels after 4DF application." (PMID 34357446, 2021). "However, CRP is not useful for diagnosis of early stages of endometriosis." (PMID 21827658, 2011). "Other biomarkers, such as C-reactive protein (CRP), Ca 19-9, folistatin, activin A, and anti-Müllerian hormone, have been reported to show alterations, but none have proven to be substantially specific for endometriosis." (PMID 39852162, 2025).
Lymphadenopathy (43 papers, 2008 to 2026). Enlargement (swelling) of a lymph node. "From the adult study from KwaZulu-Natal, associations included C-reactive protein above 25 mg/L, lower haemoglobin, more weight loss and radiological evidence of lymphadenopathy." (PMID 31260455, 2019). "For unmasking OI (predominantly TB) IRIS, the risk factors we identified were all consistent with the presence of sub-clinical disease, in particular lymphadenopathy present on chest X-ray, low haemoglobin, greater than 10% weight loss, and high baseline CRP." (PMID 23152745, 2012). "Our clinical prediction model, incorporating established risk factors (age, CA19-9, CEA, disease duration <1 month, CRP, surgical history, lymphadenopathy), achieved an AUC of 0.83 (95% CI:0.70-0.96), aligning with prior reports (AUC 0.75-0.83) while maintaining practical clinical utility." (PMID 40678070, 2025). "It was not until 4 months later that the patient presented with another episode of anasarca and was found to have diffuse lymphadenopathy and elevated CRP (145 mg/L)." (PMID 41220922, 2025). "The patient's condition improved with complete resolution of lymphadenopathy, improvement of dyspnea, normalization of CRP (0.3 mg/dL), and resolution of pleural effusion and ascites." (PMID 41220922, 2025). "Clinical features such as dyspnoea, sore throat, lymphadenopathy, comorbid chronic conditions, and elevated CRP were sign ificantly correlated with age group (0–6 months, 6–24 months, and >24 months of age) in SARS-CoV2 infections (p < 0.05, χ2)." (PMID 41305426, 2025). "Linear regression showed that presence of metastasis in the liver is significantly associated with MMP-9 values after procedures (Beta = −0.911, p = 0.049) when adjusted for baseline MMP-9 values, presence of lymphadenopathy, CRP, and glucose." (PMID 36837539, 2023). "Blood tests, such as complete blood count (CBC) with differential, erythrocyte sedimentation rate and C-reactive protein (CRP), are commonly performed in children with lymphadenopathy." (PMID 37892252, 2023). "All symptoms quickly improved with amelioration of general status, local inflammatory signs, disappearance of lymphadenopathy, normalisation of CRP and decrease of serum gammaglobulin level." (PMID 35846183, 2022). "When looking at the overall clinical picture, taking into account AEs, laboratory abnormalities (CRP, neutrophils and lymphocytes), vital signs and lymphadenopathy, the maximum intensity of the flu-like symptoms was mild." (PMID 36582243, 2022). "KD and MIS-C share several common symptoms, such as skin rash, lymphadenopathy, strawberry tongue, coronary artery dilatation and an elevation inflammatory biomarkers such as C-reactive protein, procalcitonin, ferritin." (PMID 33494415, 2021). "Within a short time, the patient deteriorated with high fever, elevated CRP (50 mg/l), and increasing hepatosplenomegaly and lymphadenopathy (liver 22 cm, spleen 26 cm)." (PMID 27338827, 2016). "By logistic regression we investigated associations between F. necrophorum-positivity and pre-specified criteria: age 13–30 years, symptom duration ≤ 3 days, absence of viral symptoms (e.g. cough, coryza), fever, tonsillar swelling/exudate, lymphadenopathy and CRP ≥ 50 mg/L." (PMID 38609699, 2024). "People infected with TD may develop various systemic symptoms and reactions, including fever, cutaneous rash, lymphadenopathy, and elevations of C-reactive protein (CRP) and liver enzymes." (PMID 33057334, 2020). "After 4 weeks the lymphadenopathy was resolving and CRP was normal." (PMID 18442415, 2008). "Laboratory investigations showed high inflammation indices (C-reactive protein 15.56 mg/dL [< 0.5] and procalcitonin 12.1 ng/mL [0.00–0.50]), while imaging documented cervical and thoracic localization of reactive inflammatory response marked by diffuse characteristic lymphadenopathy." (PMID 41178842, 2025).
Lymphadenopathy (continued). "Laboratory investigations showed an inflammatory syndrome, with an increased C-reactive protein (CRP) of 280 mg/L, while the abdominal CT-scan showed mural thickening of the ascending colon all the way to the distal portion of the descending colon and reactive retroperitoneal lymphadenopathy." (PMID 37631384, 2023). "People with TB with lymphadenopathy had lower levels of CRP, NLR, and MLR than those without it." (PMID 38349459, 2024).
nosocomial infection (42 papers, 2011 to 2026). An infection acquired in a hospital or other healthcare setting. "In multivariable analysis, LBP, CRP, and albumin remained independently associated with nosocomial infection." (PMID 41574679, 2026). "We found that in patients with ECMO-associated nosocomial infections, the first hs-CRP level was significantly different between the surviving and non-surviving groups, suggesting that it has some predictive value for prognosis." (PMID 40104588, 2025). "Whether higher or undulating CRP levels are caused by a maintaining infectious status or recurrent complications such as nosocomial infections or other severe complications has to be elucidated in further analyses." (PMID 36991018, 2023). "Indeed, low citrulline levels are associated with elevated serum C-reactive protein (CRP) levels, an increased rate of nosocomial infections, and higher mortality in critically ill patients." (PMID 27751165, 2016). "Elevated interleukin 6, elevated ultrasensitive C-reactive protein, and decreased platelet count are potential biomarkers for predicting the prognosis of patients with ECMO-associated nosocomial infections." (PMID 40104588, 2025). "NLR and PLR have more predictive value than procalcitonin and C-reactive protein for nosocomial infection treated with VA-ECMO." (PMID 40460330, 2025). "We found that NLR and PLR, especially PLR, have more predictive value than procalcitonin and C-reactive protein for nosocomial infection in patients treated with VA-ECMO." (PMID 40460330, 2025). "HAI, healthcare-associated infection; CAI, community-acquired infection; IVDU, intravenous drug user; IVC, intravascular catheter; CRP ratio, greater or less than 37 % fall from peak value at oral switch." (PMID 36394002, 2022). "Secondary endpoints included rate of nosocomial infection, time to recovery from acute illness, skin condition score, rate of transepidermal water loss (TEWL) and C-reactive protein (CRP) level." (PMID 32509290, 2020). "Inflammatory markers were measured initially upon suspicion of nosocomial infection, and CRP was again measured 12–24 h later." (PMID 30542642, 2018). "A daily CRP variation of at least 4.1 mg/dl was predictive of nosocomial infection with a Se of 92% and Sp of 71%; when combined with a serum CRP above 8.7 mg/dl, these values increased to 92 and 82%, respectively." (PMID 25430913, 2014). "Our ROC analysis demonstrates that PLR (AUC = 0.763) outperforms NLR (AUC = 0.710), PCT (AUC = 0.681), and CRP (AUC = 0.635) in predicting nosocomial infections among VA-ECMO patients, suggesting its potential as a more reliable biomarker in this specific population." (PMID 40460330, 2025). "C-reactive protein is an acute phase reactant, so its persistence may represent an emerging subclinical nosocomial infection or unresolved inflammation in critically ill patients." (PMID 30717340, 2019). "Primary outcome was the “incidence density” of nosocomial infections defined as periods of elevated C-reactive protein (>10 mg/L) from day 7 after initiation of milk feedings until the 42nd day of life (number of nosocomial infections/total number of patient days)." (PMID 23401695, 2013). "However, these associations were no longer statistically significant after adjustment for Acute Physiology and Chronic Health Evaluation II scores, Sequential Organ Failure Assessment scores, and C-reactive protein level, corticosteroid use and nosocomial infection." (PMID 37193970, 2023). "In this context, nosocomial infections should be primarily identified, often aided by laboratory data, such as white blood cell (WBC) counts, and inflammation indices like C-reactive protein (CRP) and procalcitonin." (PMID 41139354, 2025). "According to existing studies, WBCs, PMN, CRP, and PCT are all involved in systemic inflammatory responses following CPB and are sometimes related to nosocomial infection after congenital heart disease surgery." (PMID 36111236, 2022).
nosocomial infection (continued). "Our study is the third one comparing CRP and PCT and the second one comparing their courses in the evolution of nosocomial infection in the general critically ill patient with new onset fever." (PMID 23762396, 2013). "However, the composite score had by far the highest positive predictive value (87% vs. 47%), suggesting that it could best be used in encouraging clinicians to initiate antimicrobial therapy when faced with a suspected diagnosis of nosocomial infection and a CRP over 88 mg/L." (PMID 23547830, 2013). "ROC curves were plotted to compare the detection of nosocomial infection by PCT, CRP, WBC, and temperature at D0." (PMID 23547830, 2013). "The epidemiology of infection during ECMO varies widely, and the diagnosis of nosocomial infection remains challenging, with a lack of evidence supporting biomarkers such as procalcitonin and C-reactive protein." (PMID 35991647, 2022). "Combining CRP, PCT and temperature is an approach which may increase of nosocomial infection detection in the ICU." (PMID 23547830, 2013). "Our study suggesting greater value of decreases in CRP than of PCT in resolving nosocomial infection in the ICU, does also not agree with the reported superior value of PCT decreases in predicting response of infections to treatment." (PMID 23762396, 2013). "The sequential measurements of serum PCT and CRP might be reliable and complementary biomarkers in early identification of ICU-acquired nosocomial infection." (PMID 23547830, 2013). "AUCs for PCT and CRP D0 were 0.84 and 0.88 respectively, and were not significantly different (p = 0.67) indicating that the tests globally performed similarly in discriminating nosocomial infection." (PMID 23547830, 2013). "It must also be acknowledged that CRP at D0 had a negative predictive value higher than our composite score (97% vs. 94%), showing that low CRP, under the threshold of 88 mg/L could assist clinicians in eliminating the diagnosis of nosocomial infection." (PMID 23547830, 2013). "Another study found specificity (83%) and sensitivity 69%, for combined CRP and IL-8 for discriminating bacerial pneumonia from PJP or mycobateriosis, in a cohort that included hospital-acquired infections and non-tuberculous mycobacterial infections." (PMID 30107791, 2018). "Time-dependent analysis of both PCT and CRP during the 4 days prior to diagnosis of nosocomial infection showed a significant increase in infected patients whereas PCT and CRP levels decreased over the time in the non-infected group." (PMID 23547830, 2013). "Compared with noninfected patients, those with nosocomial infection had higher WBC, CRP, PCT, LBP, lactate, international normalized ratio (INR), and total bilirubin (TB), lower albumin and sodium, a higher neutrophil-to-lymphocyte ratio (NLR), and a lower lymphocyte-to-monocyte ratio (LMR)." (PMID 41574679, 2026). "Patients with trajectory 2 showed a rapid increase in CRP values, representing a possible nosocomial infection in the ICU; however, the subsequent decrease in CRP levels could not be observed due to time constraints." (PMID 37709919, 2023). "In addition, normal levels of CRP and PCT rule out hospital-acquired infections in SE patients." (PMID 22099124, 2011). "In addition, low levels of CRP and PCT rule out hospital-acquired infections in SE patients." (PMID 22099124, 2011).
coronary stenosis (41 papers, 2012 to 2026). Narrowing of the coronary artery lumen diameter. "In multivariate logistic regression analysis, endocan (p < 0.001, 95% CI: 1.010-1.035), BMI (p = 0.020, 95% CI: 1.070-2.237), and CRP (p = 0.039, 95% CI: 1.003-1.099) were independently associated with clinically significant coronary stenosis." (PMID 42318145, 2026). "We uncovered the pathophysiological basis underlying the association between biomarkers of inflammation and coronary artery events by showing that hs-CRP is associated with the functional severity of coronary artery stenosis." (PMID 34386531, 2021). "First, in a cross-sectional design covering 1920 patients with T2DM from two provinces in China, mtDNA 8-OHdG was positively associated with CAD presence, coronary stenosis severity, and CRP levels." (PMID 32075646, 2020). "Studies even found the TT genotype, which leads to lower levels of galectin-2, to be associated with more severe coronary stenosis and higher levels of C-reactive protein." (PMID 27903268, 2016). "However, in the same multivariable analyses, age, male sex, and CRP ≥5 was significantly associated with having significant coronary stenosis, and age, male sex and statin use for increased calcium score." (PMID 35476713, 2022). "In patients with significant coronary stenosis, coronary flow reserve has been correlated with vulnerable plaques and elevated CRP levels." (PMID 41302972, 2025). "Studies have shown a correlation between elevated high-sensitivity C-reactive protein and coronary stenosis and severity of stenosis." (PMID 35621834, 2022). "Hs-CRP was predictive of the functional severity of coronary artery stenosis of target vessel as detected by cQFR, and a cut-off value of hs-CRP = 1.45 conferred a sensitivity of 79.2% and a specificity of 59.5%." (PMID 34386531, 2021). "CRP positively correlated with coronary stenosis severity (rho = 0.3, p=.05) and negatively related with left ventricle ejection fraction (LVEF) at 1 month (rho= −0.43, p=.05)." (PMID 34180324, 2021). "Multivariable stepwise logistic regression analysis showed that both hs-CRP and LF were independent predictors of functional severity of coronary stenosis of target vessel (all P < 0.05)." (PMID 34386531, 2021). "For the predictability of the functional severity of coronary stenosis of target vessel, the positive Youden index of the combined hs-CRP increased in model 4 (AUC: 0.881; C-index: 0.897; Youden index: 0.672; sensitivity: 89.6%; specificity: 73.1%; P < 0.001)." (PMID 34386531, 2021). "When we pooled non-CHD subjects and CHD patients together, the V-plot confirmed the results of logistic analyses by showing that HSPCs, CRP, white blood cell count, neutrophil count and LDL-c were associated with significant coronary stenosis ≥70% vs. <70%." (PMID 30737465, 2019). "For CHD patients, per one-SD increase of each variable, the odds ratio of having mild vs. severe coronary stenosis was 2.08 for HSPCs (p = 0.0009), 1.67 for CRP (p = 0.026), and 1.67 for LDL-c (p = 0.014)." (PMID 30737465, 2019). "In this study, patients with more severe coronary stenosis had higher CRP levels and a lower left ventricular ejection fraction (LVEF)." (PMID 27446957, 2016). "The secondary outcomes include the degree of coronary stenosis, coronary artery calcification score, Gensini score, Seattle Angina Questionnaire score, high-sensitivity C-reactive protein, matrix metalloproteinase-9, blood lipids, and carotid artery ultrasound parameters." (PMID 39012918, 2024). "A measurable Hs-CRP is a potential marker of coronary stenosis." (PMID 35621834, 2022). "We are unable to comment on the potential associations of the severity of atheromatosis with CRP levels in MINOCA since the data available in SWEDEHEART do not allow for a subclassification of patients with coronary stenosis <50%." (PMID 34032303, 2021). "We found a positive correlation between CRP and the severity of coronary stenosis." (PMID 34180324, 2021).